CX3CR1 (C-X3-C motif chemokine receptor 1)
Diseases named in the same sentence as CX3CR1 in open-access papers (continued):
Sharing a sentence is not in itself a finding about the gene and the disease.
colitis (continued). "Conditional knockout (cKO) of Hdac3 in CX3CR1 positive cells attenuated the disease severity of Dextran Sulfate Sodium (DSS)-induced colitis." (PMID 38903915, 2024). "The FBXW7/EZH2/CCL2/CCL7 pathway has been shown to exacerbate colitis severity by recruiting CX3CR1 proinflammatory MPhs." (PMID 39568749, 2024). "In a model of DSS-induced colitis, transferred monocytes differentiated into colonic Cx3cr1-GFPInt Ly6CLow cells and Cx3cr1-GFPHi Ly6CLow resident macrophages." (PMID 39430099, 2024). "In this model, IL-10 signaling in CX3CR1+ macrophages is crucial for preventing spontaneous colitis." (PMID 39379604, 2024). "In a monocyte-focused study, interruption of the fractalkine–CX3CR1 axis ameliorated colitis through regulation of intravascular monocyte behaviors on the venous endothelium of inflamed colons in oxazolone-induced colitis models." (PMID 36737792, 2023). "One study reported an improvement in oxazolone-induced colitis through the administration of an anti-fractalkine monoclonal antibody with a reduction in colonic CX3CR1+ macrophages." (PMID 37998910, 2023). "It has been confirmed that the occurrence of gut inflammation, as the first line of defense in the intestinal immune response, can affect CX3CR1+ macrophage count, which can indicate the severity of inflammation in mice with colitis." (PMID 37157929, 2023). "In C. rodentium‐induced colitis, deletion of CX3CR1+ macrophages resulted in reduced secretion of IL‐22 by innate lymphoid ILC3, leading to the decreased production of AMPs in colonic epithelium and delaying colonic clearance of C. rodentium." (PMID 35593111, 2022). "In mice, mycobiota changes induced by antifungal treatment were found to exacerbate both colitis and allergic airway disease, which involves gut-resident CX3CR1+ mononuclear phagocytes." (PMID 37746206, 2022). "Lack of CX3CR1+ mononuclear phagocytes affects gut mycobiome composition and results in colitis in mice, and CX3CR1 defects are found in some Crohn’s disease patients." (PMID 37746206, 2022). "If the conditional deletion of CD98hc affects the development of CX3CR1+ intestinal monocytes and macrophages, presumably, this will impact the colitis severity." (PMID 32188932, 2020). "The conditional deletion of CD98hc in CX3CR1+ macrophages and their progenitors resulted in attenuated chemically-induced colitis and in an altered macrophage development with reduced numbers MHCII+ macrophages in the colonic lamina propria." (PMID 32188932, 2020). "In line with this, Cx3cr1-deficient mice have been shown to be more susceptible to chemically-induced colitis, although this has been contested by other reports showing that Cx3cr1 deficiency suppresses DSS-induced and T cell transfer colitis." (PMID 30538701, 2018). "Because the Cx3cr1+/gfp reporter mice are IL-10 sufficient, we had to induce colitis by H. hepaticus inoculation plus weekly administration of anti-IL-10R monoclonal antibody (MAb)." (PMID 29203542, 2018). "Pro-inflammatory lamina propria-derived TNF-α can also exacerbate colitis through CX3CR1+ DCs indicating that this DC subset also plays role in the maintenance of balanced inflammatory and/or standby conditions upon gut homeostasis." (PMID 28458670, 2017). "These monocyte-derived CD103(+)CX3CR1(−) cells accumulated in the intestinal lamina propria during both T cell-mediated colitis and Trichuris muris infection, and then migrated to the mesenteric lymph nodes." (PMID 23166492, 2012). "To date, targeting of chemokine receptors such as CCR2, CCR5, CCR6, CXCR3, CXCR4 and CX3CR1 by gene disruption or antagonistic peptides has been found to protect animals from DSS colitis." (PMID 21283540, 2011). "CX3CR1 positive macrophage are the resident monocytes and are significantly expanded in the acute phase inflammation in colitis, however, whether HDAC3 is involved in the process is unknown." (PMID 38903915, 2024).
colitis (continued). "Similarly, CD11c+ CX3CR1+ macrophages have also been identified as crucial IL-23-producing cells in Hh-induced colitis." (PMID 39379604, 2024). "To verify whether CX3CR1-positive monocytes HDAC3 is involved in the development of colitis, we conditionally knocked out HDAC3 in CX3CR1 positive monocytes (HDAC3 cKO) by crossing HDAC3f/f mice with CX3CR1cre mice." (PMID 38903915, 2024). "To verify whether TQHXD protected the gut from inflammation via CX3CR1, we subjected CX3CR1GFP/+ and CX3CR1GFP/GFP reporter mice, in which CX3CR1 is replaced with GFP on macrophages in one and two alleles, respectively, to a TBI‐induced colitis model." (PMID 37157929, 2023). "In this regard, it will be worthwhile to further investigate whether CX3CR1+ macrophages contribute to iNKT cell-mediated host defenses during enteropathogen-induced colitis." (PMID 38274786, 2023). "In addition, CX3CR1 modulates bacterial translocation, intestinal macrophage homeostasis, as well as colitis Th17 responses in mice." (PMID 35996406, 2022). "Similarly, colitis rats receiving feed with low-molar-mass oat beta-glucan (βGl+) upregulated the expression of only four genes (Ccl19, Cxcl10, Cx3cr1, Cxcr5) in this stage of colitis." (PMID 35163326, 2022). "Moreover, although mature lamina propria macrophages express Cx3cr1,18 the results comparing Ltbr deletion using Mrp8-Cre to Cx3cr1-Cre ERT were striking in showing that only the neutrophil-specific gene deletion augmented colitis severity." (PMID 33568785, 2021). "On the other hand, studies with the dextran sulfate sodium (DSS)-induced colitis model, antibiotics induced colitis model and Myd88-knockout mouse model all reach identical conclusions that CX3CR1+ dendritic cells have strong ability of migration to mLNs and antigen presentation." (PMID 32153586, 2020). "Indeed similar to our study it has recently been shown that specific deletion of the Il10ra in CX3CR1+ cells elicits spontaneous colitis in a Helicobacter positive facility." (PMID 27027442, 2016). "CX3CR1-deficient and CX3CL1-deficient mice were reported to be relatively protected from acute, DSS-induced colitis – a phenotype that might be related to TED formation." (PMID 26082775, 2015). "Importantly, the suppression of ILC3s by Treg cells contributes to repressing ILC3-mediated colitis, indicating that promoting the function of Treg cells or limiting the activity of CX3CR1+ macrophages would be a promising therapeutic option for treatment of IBD." (PMID 41467015, 2025). "Furthermore, CX3CR1+ MNP-secreted TNF-like ligand 1A (TL1A) in response to IBD-associated microbiota promotes OX40L expression on MHCII+ ILC3s, which further co-stimulates pathogenic Th1 cell expansion and consequently induces chronic T cell colitis." (PMID 41467015, 2025). "IL-23 production by cDCs may be protective in acute colitis models such as DSS-induced colitis, whereas IL-23 upregulation by CX3CR1+ macrophages exacerbates chronic colitis models, including those induced by IL-10 deficiency or anti-CD40 agonistic antibody injection." (PMID 39379604, 2024). "While CX3CR1+ macrophages have been highlighted as a source of IL-23 in animal models of colitis, the involvement of IL-23-producing cDCs located in tertiary lymphoid tissues, which are crucial during C. rodentium infection, in exacerbating IBD pathology remains unclear." (PMID 39379604, 2024). "However, the mechanism of CX3CR1-positive monocytes in colitis is unclear." (PMID 38903915, 2024). "Also, the severity of DSS-induced colitis in mice could be limited by the transfer of CX3CR1 macrophages." (PMID 37953266, 2023). "Notably, pharmacologic inhibition HO-1 by ZnPP administration aggravated the dextran sulfate sodium-induced colitis, whereas the HO-1 inducer CoPP treatment ablated intestinal inflammation and fully protected CX3CR1 KO mice from azoxymethane and dextran sulfate sodium-induced colon carcinogenesis." (PMID 33801351, 2021).
colitis (continued). "Indeed, double inactivation of both IL-10R and IL-23 in CX3CR1 macrophages (Il10raflox/floxIl23aflox/flox Cx3cr1-Cre mice) protected mice from colitis development, and moreover, Il10raflox/flox Cx3cr1-Cre mice lacking IL-22 (Il10raflox/flox Cx3cr1-Cre Il22−/− mice) did not develop colitis." (PMID 33562334, 2021). "In contrast, another more recent study showed that CX3CR1 and CX3CL1 were highly upregulated in the colon during experimentally induced colitis and that Cx3cl1-deficient mice and two different strains of Cx3cr1-deficient mice developed more severe colitis as compared to controls." (PMID 32987848, 2020). "In a dextran sulfate sodium-induced colitis mouse model, oral administration of EPICERTIN reduced neutrophil infiltration and increased CX3CR1+MHCIIlo/- (M2-like) over CX3CR1+MHCIIhi (M1-like) macrophages in the colon lamina propria." (PMID 41651223, 2026). "Flow cytometry was performed on brain single cell suspensions to further characterize activated microglia during acute colitis using several markers, including CD45, CD11b, P2RY12, CD11c, CD68, CX3CR1, and LAMP1." (PMID 40457749, 2025). "Conversely, the depletion of CX3CR1+ macrophages with an anti-CSF1R antibody significantly decreases the levels of IL-23 and attenuates the severity of colitis." (PMID 39379604, 2024). "Therefore, the CX3CR1-positive monocytes HDAC3 may be a therapeutic target for colitis." (PMID 38903915, 2024). "During naive CD4+ T cell transfer-mediated colitis, CD4+ T cells are in close contact with colonic CX3CR1+ phagocytes that present bacterial-derived Ags." (PMID 38274786, 2023). "CX3CR1+ MNPs induce Th17 cell differentiation and responses, induce IgG responses to C. albicans, and promote the activation of the inflammasome in DSS colitis." (PMID 37998910, 2023). "LAG-3 on Tregs was also highlighted in an innate-like cell 3-driven experimental inflammatory model of colitis, where LAG-3+ Tregs specifically targeted CX3CR1+ macrophages, decreasing their production of IL-23 and IL-1β, ameliorating disease." (PMID 34907325, 2021). "We show that the conditional deletion of CD98hc in CX3CR1+ monocytes and macrophages altered their development to mature MHCII+ macrophages, increased the expression of apoptotic genes and attenuated colitis." (PMID 32188932, 2020). "CX3CR1+ macrophage-derived IL-10 is not required to tame colitis in mice; however, IL-10R expressed by macrophages is essential to prevent fulminant enterocolitis with upregulated pro-inflammatory genes, including Nos2, Il23a, Ccl5, Ccr7, and Saa3." (PMID 33562334, 2021). "The CXCR4 expression did not change, however, CX3CR1− fibrocytes gradually increased with the development of colitis." (PMID 31189971, 2019). "In the circumstance of DSS-induced colitis, we found iron supplementation resulted in more infiltration of inflammatory cells (e.g., CD3+ T cells and MPO+ neutrophils), and it also changed the morphology of CX3CR1+ resident macrophages surrounding intestinal crypts." (PMID 40416374, 2025). "Absence of CX3CR1 expression by colonic macrophages results in reduced secretion of IL-10 and failure in supporting lamina propria Treg cell expansion: accordingly, lack of CX3CL1-CX3CR1 signaling leads to a more sever dextran sulfate sodium (DSS)-induced colitis." (PMID 32650452, 2020). "Despite the presence of a pro-inflammatory milieu, CX3CR1+ resident macrophages still retain their anti-inflammatory activity: accordingly, genetic depletion of Cx3cr1 results in an increased inflammatory condition and tissue damage in a mouse model of DSS-induced colitis." (PMID 32650452, 2020). "CX3CR1 deficient mice could not resolve intestinal inflammation in azoxymethane (AOM)/DSS-induced colitis-associated cancer and have higher colitis score and polyps, compared with wildtype mice." (PMID 30258436, 2018).
colitis (continued). "However, the presence of microbiota provide signals for both CX3CR1+ inflammatory cells and CD11b+CD103+ DCs in the lamina propria to produce IL-23 and induce IL-22 secretion by innate lymphoid cells, thus playing a critical role in promoting mucosal healing in colitis." (PMID 28458670, 2017). "We also subjected Cx3cr1GFP/+Ccr2RFP/+ mice to DSS-induced colitis and found that no CCR2+ and/or CX3CR1+ signal co-localized with the large F4/80hi cells indicating that these are distinct cell lineages." (PMID 34911964, 2021).
glioma (48 papers, 2013 to 2026). A benign or malignant brain and spinal cord tumor that arises from glial cells (astrocytes, oligodendrocytes, ependymal cells). "We previously established that a glioma-associated CCR2+/CX3CR1+ myeloid cell population also expresses markers consistent with M-MDSCs." (PMID 36685592, 2022). "Studies have shown that mutation in the IDH1 gene, especially the R132H mutation, can promote NK cell recruitment through CX3CL1/CX3CR1 chemotherapy and are associated with a better prognosis in gliomas." (PMID 35601497, 2022). "It has been reported that neurons express chemokine CX3CL1 to recruit CX3CR1+ NKs to the brain parenchyma, which is associated with a better prognosis against e.g. glioma." (PMID 35185929, 2022). "In parallel, MG highly expressing Cx3cr1 are led towards glioma by Cx3cl1, which is secreted by glioma cells with NF1 mutation." (PMID 34671362, 2021). "For instance, bone marrow cells of Cx3cr1GFP/WT mice were used to generate chimeras for the detection of infiltrated macrophages in brain tumors by their GFP signal demonstrating pronounced CX3CR1 expression of glioma-associated macrophages." (PMID 33375505, 2020). "In humans, but not in rodent models, the prolonged average of survival time of glioma patients and the low infiltration of microglia is associated with the CX3CR1 gene." (PMID 30123112, 2018). "We observed an increase in PVA, where glioma stem cells are localized, in host Cx3cr1-deficient tumors." (PMID 25987130, 2015). "In previous genomic studies, glioma outcome and progression were shown to correlate with macrophage and microglia gene expression, while polymorphisms in the microglial CX3CR1 chemokine receptor locus were associated with improved patient survival." (PMID 24147027, 2013). "The attraction of the CX3CR1+ NK cells is associated with a better prognosis in glioma patients." (PMID 35185929, 2022). "Loss of Cx3cr1 in the host microenvironment facilitated the recruitment of Ly6CHigh “inflammatory monocytes” into tumor tissues, which were responsible for increased tumor incidence and shorter survival times in glioma-bearing mice." (PMID 29594035, 2018). "To further illustrate their functional differences, we genetically deleted Cx3cr1 from the microenvironment of PDGFB glioma-bearing mice and observed an increase in tumor incidence and a shortened survival time of stroma deficient in Cx3cr1 compared to that in Cx3cr1 wild-type stroma." (PMID 29867979, 2018). "Emerging evidence highlights the significance of NK cell infiltration, cytotoxicity, and ligand-receptor dynamics-such as NKG2D, KIRs, and CX3CR1+ subsets-in shaping prognosis and therapeutic responsiveness in glioma patients." (PMID 41929521, 2026). "More specifically, studies have shown that the CX3CL1/CX3CR1 axis is overexpressed in invading glioma cells, and when treated with neutralizing antibodies, this invasiveness is largely reduced." (PMID 38893093, 2024). "In this study, we found that bone marrow-derived CCR2+/CX3CR1+ cells adopt an immune suppressive cell phenotype when cultured with glioma-derived factors." (PMID 39272914, 2024). "We determined that bone marrow-derived CCR2+/CX3CR1+ cells adopt an immune suppressive cell phenotype when cultured with glioma-derived factors." (PMID 39272914, 2024). "While CX3CL1 and its receptor CX3CR1 are low expressed in cluster B, which have been proven to negatively regulate glioma invasiveness." (PMID 38181024, 2024). "Other markers for microglia in homeostatic conditions, such as Cx3cr1, Sall1, and Tmem119, are also downregulated in glioma." (PMID 37365324, 2023). "The development of fate-mapping models, such as Cx3cr1-CreER mice, now makes it possible to distinguish these two populations in mice with glioma." (PMID 37365324, 2023). "KR158B-CCL2 and -CCL7 knockdown murine gliomas contain equivalent percentages of CCR2+/CX3CR1+ MDSCs compared to KR158B gliomas." (PMID 36685592, 2022).